FAM225B (family with sequence similarity 225 member B)
Synonyms: C9orf110; LINC00256B; NCRNA00256B
Gene: Long non-coding RNA gene on chromosome 9 (113,095,149 to 113,111,543, reverse strand). Ensembl gene ENSG00000225684.
Diseases named in the same sentence as FAM225B in open-access papers:
FAM225B is named in the same sentence as 12 diseases in open-access papers, as found by Europe PMC text mining. Sharing a sentence is not in itself a finding about the gene and the disease. The quoted sentences say what the papers report.
nasopharyngeal carcinoma (4 papers, 2022 to 2024). A carcinoma arising from the nasopharyngeal epithelium. "According to the previous studies, lncRNA FAM225B expression is dramatically elevated in nasopharyngeal carcinoma and recurrent glioblastoma, and lncRNA FAM225B knockdown restricts cell proliferation, migration, and invasion." (PMID 37720188, 2023). "For instance, FAM225B directly bound to miR-613, a miRNA targeting CCND2, resulting in CCND2 upregulation, facilitating nasopharyngeal carcinoma tumorigenesis and metastasis." (PMID 35037556, 2022).
glioblastoma (3 papers, 2020 to 2024). The most malignant astrocytic tumor (WHO grade IV). "Additionally, FAM225B can serve as a prognostic biomarker for glioblastoma and may be a potential therapeutic target for glioblastoma treatment." (PMID 38334964, 2024).
ovarian carcinoma (3 papers, 2023 to 2025). A malignant neoplasm originating from the surface ovarian epithelium. "FAM225B overexpression inhibits ovarian cancer cell proliferation, migration, invasion, while promotes apoptosis." (PMID 41322492, 2025). "Serum expression of lncRNA FAM225B was reduced in ovarian cancer patients compared to healthy individuals." (PMID 39022688, 2024). "A decrease in proliferation, metastasis and invasion of ovarian cancer cells was found by restoring the expression of lncRNA FAM225B." (PMID 39022688, 2024). "In this study, we aimed to determine the underlying mechanism of the lncRNAs FAM225B and PDIA4 in ovarian cancer development." (PMID 37720188, 2023). "This research study supports the fact that lncRNA FAM225B in ovarian cancer can upregulate PDIA4 by directly binding to DDX17, inhibiting the activities of ovarian cancer cells." (PMID 37720188, 2023). "We observed a low expression level of lncRNA FAM225B in ovarian cancer that lncRNA FAM225B overexpression suppressed ovarian cancer progression and that lncRNA FAM225B suppression exhibited an inverse trend." (PMID 37720188, 2023). "To determine if FAM225B regulates PDIA4 expression in ovarian cancer, we tested the phenotypes of the cells after transfection or cotransfection with lncRNA FAM225B- and PDIA4-related vectors." (PMID 37720188, 2023). "Downregulation of PDIA4 expression counteracts the suppressive effect of lncRNA FAM225B overexpression in ovarian cancer cells." (PMID 37720188, 2023). "In conclusion, the main findings of our study indicate that lncRNA FAM225B plays an inhibitory role in ovarian cancer via the DDX17/PDIA4 axis." (PMID 37720188, 2023). "To elucidate the effect of lncRNA FAM225B on the development of ovarian cancer, we transfected both the FAM225B overexpression- and silenced expression-related vectors into SKOV3 and OVCAR-3 cells." (PMID 37720188, 2023). "Therefore, in ovarian cancer, lncRNA FAM225B promotes PDIA4 expression through DDX17, which in turn inhibits ovarian cancer progression." (PMID 39022688, 2024). "To determine whether PDIA4 participates in the molecular mechanism of lncRNA FAM225B in the development of ovarian cancer, we predicted that lncRNA FAM225B would inhibit PDIA4 expression by binding to the transcription factor DDX17." (PMID 37720188, 2023). "Furthermore, to elucidate the molecular mechanism of action of lncRNA FAM225B in the development of ovarian cancer, we verified the direct interaction between lncRNA FAM225B and transcription factor DDX17 in ovarian cancer cells using RNA pull-down and RIP assays." (PMID 37720188, 2023). "The expression levels of long non-coding RNA FAM225B and protein disulfide isomerase family member 4 (PDIA4) are reduced in ovarian cancer cells." (PMID 41322492, 2025). "In ovarian cancer cells, the binding of FAM225B to DDX17 upregulates the expression of PDIA4, which in turn inhibits the progression of ovarian cancer cells." (PMID 41322492, 2025). "The results suggest that the lncRNA FAM225B can increase PDIA4 expression by combining with DDX17, inhibiting the process of ovarian cancer." (PMID 37720188, 2023). "The expression of lncRNAs FAM225B and PDIA4 was decreased in the serum of patients with ovarian cancer and cell lines." (PMID 37720188, 2023). "In this study, we demonstrated that lncRNA FAM225B elevates PDIA4 by directly binding to DDX17, restricting the biological function of ovarian cancer cells." (PMID 37720188, 2023). "To further verify the differential expression of FAM225B and PDIA4 in ovarian cancer cells, we tested their expression levels in ovarian cancer cell lines." (PMID 37720188, 2023). "However, the role of FAM225B in ovarian cancer remains unclear." (PMID 37720188, 2023). "First, lncRNA FAM225B and PDIA4 expression levels in the serum of patients with ovarian cancer (cancer group) and HCs were determined using RT-qPCR and Western blot assays." (PMID 37720188, 2023).
ovarian carcinoma (continued). "RT-qPCR and Western blot assays were performed to detect the expression levels of the lncRNAs FAM225B, DDX17, and PDIA4 in the serum of patients with ovarian cancer and cell lines." (PMID 37720188, 2023). "This study aimed to explore the roles and mechanisms of lncRNA FAM225B and PDIA4 in ovarian cancer." (PMID 37720188, 2023). "This suggests that FAM225B and PDIA4 are involved in ovarian cancer." (PMID 37720188, 2023). "It was hypothesized that the lncRNAs FAM225B and PDIA4 expression were reduced in ovarian cancer cells compared with HOSEPIC cells (P < 0.01)." (PMID 37720188, 2023).
bladder cancer (2 papers, 2022 to 2023). "Recently, several studies reported that FAM225B was abnormally expressed in renal cell carcinoma, bladder cancer, papillary thyroid carcinoma, and glioblastoma and can be used as a candidate prognostic biomarker." (PMID 34255617, 2022). "The lncRNA family with sequence similarity 225 members B (FAM225B, also called LINC00256B) is a newly discovered lncRNA whose expression is altered in several cancers, such as renal cell carcinoma, bladder cancer, and papillary thyroid carcinoma." (PMID 37720188, 2023).
glioma (2 papers, 2020 to 2022). A benign or malignant brain and spinal cord tumor that arises from glial cells (astrocytes, oligodendrocytes, ependymal cells). "This indicated that FAM225B was associated with glioma malignancy and may serve as a potential indicator for glioma grade." (PMID 33299501, 2020). "Herein, nine ferroptosis-related lncRNAs (AC062021.1, FAM66C, MIR497HG, TMEM72-AS1, AC010729.2, FAM225B, HOXA-AS2, LINC00662, and LINC00665) were identified to construct a risk model in patients with glioma." (PMID 35174152, 2022). "Then, we analyzed the expression of FAM225B in different grades of glioma, including grade II, grade III, and GBM (P < 0.0001)." (PMID 33299501, 2020). "The expression of FAM225B increased with the glioma grades, and it indicated the poor prognosis in rGBM patients." (PMID 33299501, 2020). "Then, we compared the FAM225B expression level in primary and recurrent gliomas of grade II (P = 0.0568) and grade III (P = 0.0629)." (PMID 33299501, 2020). "The result showed that the expression of FAM225B was positively correlated with the grade of gliomas." (PMID 33299501, 2020). "The expression of FAM225B increased with the grades of gliomas (P < 0.0001)." (PMID 33299501, 2020). "Compared with the primary glioma group, the expression of AC062021.1, FAM225B, LINC00662, LINC00665, and TMEM72-AS1 was significantly different in the recurrent glioma group of the training CGGA693 cohort." (PMID 35174152, 2022).
renal carcinoma (1 paper, 2024). A carcinoma arising from the epithelium of the renal parenchyma or the renal pelvis. "After the knockdown of FAM225B, the proliferation, migration, and invasion abilities of renal cancer cell lines OS-RC-2 and 786-O all decreased." (PMID 38334964, 2024).
renal clear cell carcinoma (1 paper, 2024). "After Lasso regression analysis and multifactorial Cox regression analysis, 5 lncRNAs (FAM225B, ZNF503-AS1, SPINT1-AS1, WWC2-AS2, LINC01338) emerged as independent risk factors for the prognosis of renal clear cell carcinoma." (PMID 38334964, 2024).
tumor (4 papers, 2019 to 2024). "Interestingly, loss-of-function analysis revealed that FAM225B knockdown significantly inhibited tumor growth in vitro and in vivo, and decreased the migratory and invasive capacity of NPC cells." (PMID 34255617, 2022). "The tumor weight from the FAM225B downregulation group was markedly decreased compared with the control group." (PMID 34255617, 2022). "Furthermore, highly expressed FAM225B was closely correlated with advanced TNM (tumor, node metastases) stage, distant metastasis, and poor overall survival." (PMID 34255617, 2022). "From the results, it is evident that FAM225B and WWC2- AS2 are highly expressed in multiple tumor cell lines." (PMID 38334964, 2024). "On the basis of the levels of lncRNAs FAM225B and PDIA4 in tumor cell lines, we chose the SKOV3 and OVCAR-3 cell lines for further research." (PMID 37720188, 2023).
cancer (2 papers, 2022 to 2023). A tumor composed of atypical neoplastic, often pleomorphic cells that invade other tissues. "Family with sequence similarity 225 members B (FAM225B) is a novel lncRNA that has been implicated in several human cancers, yet its role in the context of NPC remains largely unclear." (PMID 34255617, 2022). "Thus, we inferred that lncRNA FAM225B might have a triggering or suppressive effect on the biological processes of various cancer forms." (PMID 37720188, 2023).
FAM225B also shares sentences with these, for which no sentence is quoted: autoimmune disease (1 paper); papillary thyroid carcinoma (1); renal cell carcinoma (1).